EZH2 (enhancer of zeste 2 polycomb repressive complex 2 subunit)
Diseases named in the same sentence as EZH2 in open-access papers (continued):
Sharing a sentence is not in itself a finding about the gene and the disease.
lung adenocarcinoma (continued). "Here, we show that EZH2 suppression reduced growth of human lung adenocarcinoma A549 cells in 2D cultures but stimulated growth in 3D cultures." (PMID 37992808, 2024). "Our study found higher levels of EZH2 mRNA and protein in lung adenocarcinoma than in adjacent tissues." (PMID 37069494, 2023). "In conclusion, these findings support the probability that EZH2 appears to assume an immunomodulatory function in lung adenocarcinoma." (PMID 37069494, 2023). "Calcium/Calmodulin dependent protein kinase II alpha (CAMK2A), a key calcium signaling molecule, phosphorylates EZH2 at T487 with suppression of EZH2 activity to support Tumor initiating cells (TIC) maintenance in lung adenocarcinoma." (PMID 37803297, 2023). "Using a genetic model to delete Ezh2 in KRAS-driven lung adenocarcinomas, we observed that Ezh2 haplo-insufficient tumors were less lethal and lower grade than Ezh2 fully-insufficient tumors, which were poorly differentiated and metastatic." (PMID 36670102, 2023). "MK-1775, MK-5108, fenbendazole, albendazole, BAY-K8644, evodiamine, purvalanol-a, mycophenolic-acid, PHA-793887, and cyclopamine are potential drugs for patients with lung adenocarcinoma and high EZH2 expression." (PMID 37069494, 2023). "The EZH2 gene expression of lung adenocarcinoma was positively correlated with the gene expression of BRAF (r = 0.2633, p < 0.0001) and KRAS (r = 0.31229, p < 0.0011)." (PMID 37069494, 2023). "Consistent with previous reports, higher EZH2 expression correlated with significantly worse relapse-free survival in lung adenocarcinoma." (PMID 36670102, 2023). "Further analysis revealed that 360 lung adenocarcinoma cases with low expression of EZH2 had a median survival time of 119.87 months, compared to 357 cases with high expression of EZH2 (HR = 1.27, 95% CI 1.01−1.6, p < 0.05)." (PMID 37069494, 2023). "In lung squamous cell carcinoma and lung adenocarcinoma, EZH2 expression is positively correlated with BRAF (r = 0.2397, p < 0.0001) and KRAS (r = 0.3167, p < 0.001) gene expression." (PMID 37069494, 2023). "EZH2, on the other hand, has been shown to suppress tumor growth in lung adenocarcinoma and myelodysplastic syndrome." (PMID 38036730, 2023). "TCGA data demonstrate a correlation between high EZH2 expression and smoking (p < 0.0001), particularly in lung adenocarcinoma (p = 0.0011)." (PMID 37069494, 2023). "Data obtained in our study demonstrated that miR‐126‐5p‐mediated EZH2 exerted suppressive effects on proliferation, invasion and inducing effect on lung adenocarcinoma cell radiosensitivity and apoptosis via interaction between KLF2 and BIRC5." (PMID 35322532, 2022). "EZH2-expressing lung adenocarcinomas were more frequently to show PD-L1 protein expression than EZH2-negative cases." (PMID 36532284, 2022). "Upregulated EZH2 promotes lung adenocarcinoma cell invasiveness and metastasis in contribution to the progression of lung adenocarcinoma." (PMID 35322532, 2022). "At the same time, it has been explored that EZH2 contributes to the radioresistant phenotype of lung adenocarcinoma cells, providing the novel insights for investigating clinical treatment targets." (PMID 35322532, 2022). "Next, 2462 interacting proteins of EZH2 were found in the GeneCards database, which were intersected with the significantly lowly‐expressed DEGs in lung adenocarcinoma, then 53 genes were collected." (PMID 35322532, 2022). "In the respiratory system, TP73-AS1 promotes tumor growth and cell cycle progression of NSCLC via a pathway involving TP73-AS1/miR-449a/EZH2 or through the regulation of miR-21 which controls the progression of lung adenocarcinoma through the PI3K/AKT axis." (PMID 35614413, 2022). "The obtained data indicated that miR‐126‐5p promoted radiosensitivity of lung adenocarcinoma cells via the EZH2/KLF2/BIRC5 axis while overexpressed BIRC5 reversed the action of miR‐126‐5p." (PMID 35322532, 2022).
lung adenocarcinoma (continued). "Collectively, miR‐126‐5p downregulated EZH2 to facilitate the sensitivity of lung adenocarcinoma cells to radiotherapy via KLF2/BIRC5." (PMID 35322532, 2022). "We then study the effect of miR‐126‐5p regulating the EZH2/KLF2/BIRC5 axis on the radiosensitivity of lung adenocarcinoma cells." (PMID 35322532, 2022). "Both in vitro and in vivo experiments verified that elevated miR‐126‐5p inhibited cell migration and promoted apoptosis to enhance the sensitivity of lung adenocarcinoma cells to radiotherapy via the EZH2/KLF2/BIRC5 axis." (PMID 35322532, 2022). "Just as reported, LINC00467 promoted lung adenocarcinoma proliferation, migration and invasion by binding with EZH2 and repressing HTRA3 expression." (PMID 33996559, 2021). "For example, elevated levels of EZH2, a methyltransferase associated with PRC2, drives tumor progression in mouse models of lung adenocarcinoma through the establishment of a unique super-enhancer landscape." (PMID 34236315, 2021). "TCGA data shows that high expression of EZH2 is related with smoking (p < 0.0001), especially in lung adenocarcinoma (p = 0.0011)." (PMID 33299862, 2020). "The results from the Kaplan-Meier survival curve database also suggest that EZH2 in lung adenocarcinoma predicts a poor prognosis." (PMID 33299862, 2020). "Further analysis showed that 357 cases of lung adenocarcinoma with EZH2 high expression had a median survival time of 90 months and 360 cases with EZH2 with low expression had a median survival time of 119.87 months (HR = 1.27and 95% CI 1.01−1.6; p < 0.05)." (PMID 33299862, 2020). "In our study, the immunoreactivity of Twist (23.6% vs. 3.3%; p = 0.013) and EZH2 (25.6% vs. 8.2%; p = 0.037) was also significantly higher in lung adenocarcinoma than in epithelial cell of the normal lung." (PMID 33291558, 2020). "The extraction results of TCGA database showed that smoking was related to the high expression of EZH2, especially in lung adenocarcinoma." (PMID 33299862, 2020). "We further analyzed independent factors for EZH2 expression in patients with resected lung adenocarcinoma by univariate and multivariate analyses." (PMID 31042721, 2019). "EZH2 silencing in lung adenocarcinoma cells attenuates cell cycle progression, cell growth and invasion that can be linked to the re-activation of SESN1." (PMID 31857853, 2019). "The intention of our study was to investigate the relationship between miR‐144‐3p and EZH2 as well as the effects of their interaction on cell propagation and invasiveness in lung adenocarcinoma (LUAD)." (PMID 30280514, 2018). "In lung adenocarcinomas, the KRAS mutation is a major oncogenic mutation frequently associated with the EZH2 mutation." (PMID 34991274, 2018). "However, EZH2 suppression had an opposite effect on the 3D spheroid growth of lung adenocarcinoma A549 cells." (PMID 37992808, 2024). "However, the mechanism by which miR‐126‐5p affects radiosensitivity of lung adenocarcinoma cells by targeting EZH2 is still poorly understood." (PMID 35322532, 2022). "Furthermore, this study also indicated that EZH2 inhibited KLF2 expression to repress the radiosensitivity of lung adenocarcinoma cells." (PMID 35322532, 2022). "Existing literature indicated that EZH2 was upregulated in lung adenocarcinoma cells." (PMID 35322532, 2022). "In addition, the findings in this study proved that miR‐126‐5p targeted and inhibited EZH2 expression to facilitate the radiosensitivity of lung adenocarcinoma cells." (PMID 35322532, 2022).
lung adenocarcinoma (continued). "Therefore, it can be concluded that miR‐126‐5p facilitated proliferation, invasion and radiosensitivity of lung adenocarcinoma cells and repressed apoptosis by targeting EZH2 via interaction between KLF2 and BIRC5." (PMID 35322532, 2022). "Subsequently, we found higher EZH2 expression in lung adenocarcinoma tissues." (PMID 35322532, 2022). "Furthermore, LINC00152 inhibited the expression of tumour suppressor IL-24 by directly interacting with EZH2, which significantly increased the levels of Bcl-xl proteins, thus inhibiting apoptosis and promoting cell growth in lung adenocarcinoma." (PMID 35379783, 2022). "In another report, deletion of Ezh2 accelerates Kras-driven lung adenocarcinoma in a mouse model." (PMID 35269532, 2022). "Existing literature has reported that EZH2 is dysregulated in lung adenocarcinoma." (PMID 35322532, 2022). "Furthermore, LINC00152 promotes lung adenocarcinoma (LUAD) cell proliferation by interacting with the enhancer of zeste homolog 2 (EZH2) and repressing interleukin (IL)-24 expression." (PMID 34327141, 2021). "In comparison to normal lung tissue, H3K27me3 expression levels were decreased, while EZH2 expression levels were increased in lung adenocarcinoma and squamous cell carcinoma tissues, and correlated with decreased expression levels of H3K27me3 in the same tissues." (PMID 33050946, 2020). "However, another histone lysine modification enzyme, EZH2 (25.6% vs. 8.6%, p = 0.046), showed decreased immunoreactivity in BM compared with lung adenocarcinoma, indicating that the expression of MLL4 and UTX was decreased in BM." (PMID 33291558, 2020). "Furthermore, we analyzed the prognostic significance of EMT and EZH2 expression in patients divided into two subgroups, with Stage I or II-IV lung adenocarcinoma." (PMID 31042721, 2019). "Recently, it has been reported that the expressions of EZH2 and PD-L1 were positively correlated in lung adenocarcinoma, and DNA methylation could be involved in regulating PD-L1 expression." (PMID 31727135, 2019). "Vimentin is a key factor linking EMT and EZH2 in lung adenocarcinoma." (PMID 31042721, 2019). "Furthermore, we also uncovered the overexpression of some classical oncogenes (FOXA1, PCNA, EZH2) that were reported to mediate carcinogenesis in lung adenocarcinoma along with SUV39H2." (PMID 30348215, 2018). "In addition, we found that HBP1 and p21 were significantly down-regulated in lung adenocarcinoma, whereas EZH2 was significantly up-regulated in the cancer, according to bioinformatics analysis." (PMID 27129219, 2016). "However, the effects of EZH2 on Lung Adenocarcinoma (LUAD) remain elusive." (PMID 37069494, 2023). "Hence, we hypothesised that the miR‐126‐5p‐mediated EZH2 might alter radiosensitivity of lung adenocarcinoma cells." (PMID 35322532, 2022). "Moreover, EZH2 was significantly highly expressed in lung adenocarcinomas through the GEPIA2 tool." (PMID 35322532, 2022). "In addition, RT‐qPCR also confirmed elevated EZH2 in lung adenocarcinoma cells." (PMID 35322532, 2022). "Additionally, inactivating mutations or deletion of EZH2 have been identified in several types of tumor, such as Kras-driven lung adenocarcinoma and T cell precursor acute lymphoblastic leukemia, suggesting the tumor-suppressive effect of EZH2 in certain contexts." (PMID 33665162, 2020). "Results from a small cohort of 69 surgically resected lung adenocarcinomas revealed EZH2 immunopositivity in 63.8% of tumor tissues, and correlation with higher histologic grade and advanced TNM stage, suggesting that EZH2 may contribute to malignant disease progression." (PMID 33050946, 2020).
lung adenocarcinoma (continued). "Briefly, the EZH2 expression was not significantly increased in brain metastasis, unlike their primary cancer (lung adenocarcinoma), nor was it associated with the prognosis of lung adenocarcinoma patients independently." (PMID 33291558, 2020). "Zhang and colleagues successfully developed EZH2 inhibitor JQEZ5 and demonstrated its antitumour effects in EZH2-driven lung adenocarcinoma models." (PMID 40310411, 2025). "There was a downregulation of most of necroptosis-related genes in lung adenocarcinoma (LUAD) versus lung tissues but an increase in PGAM5, HMGB1, TRAF2, EZH2 levels." (PMID 37965055, 2023). "The suppression of MEIS1 expression is related with epigenetic regulation mediated by EZH2-DNMT3a and lncRNA ELFN1-AS1, cell viability and tumor growth, and CpG island methylation of squamous cell carcinomas and lung adenocarcinomas cells." (PMID 36661515, 2023). "A positive correlation exists between EZH2 expression and EGFR expression in lung squamous cell carcinoma and lung adenocarcinoma, but it is weak (r = 0.1122, p = 0.0002)." (PMID 37069494, 2023). "However, the mechanisms of EZH2 on lung adenocarcinoma (LUAD) remain unclear." (PMID 36629984, 2023). "To study the correlation of EZH2/FOXP2 expression with patient prognosis, we queried published RNA-sequencing data from The Cancer Genome Atlas using KM-Plotter39 on 366 lung adenocarcinoma samples." (PMID 36670102, 2023). "Due to the limited known researches, the roles of miR‐126‐5p, EZH2, KLF2, BIRC5 as well as their interaction in the radio‐resistance of lung adenocarcinoma cells should be more clearly investigated." (PMID 35322532, 2022). "In the interaction network diagram of 53 genes, 10 genes were at the core position (Degree ≥5), among which KLF2 was obviously downregulated in lung adenocarcinoma tissues, and there was a significant correlation between EZH2 and KLF2 in lung adenocarcinoma." (PMID 35322532, 2022). "miR‐126‐5p and KLF2 were poorly expressed, while EZH2 and BIRC5 were upregulated in lung adenocarcinoma tissues and cells." (PMID 35322532, 2022). "The objective of our study was to investigate the effect of miR‐126‐5p, EZH2, KLF2 and BIRC5 in radio‐resistance of lung adenocarcinoma cells and their inner mechanisms." (PMID 35322532, 2022). "For instance, FEZF1-AS1 can bind to LSD1 and EZH2 and epigenetically repress E-cadherin in NSCLC39 or p57 in lung adenocarcinomas." (PMID 32020063, 2020). "Although our study suggests a meaningful role for several histone lysine modification enzymes, such as UTX, MLL4, and EZH2, in regulating the expression of EMT-TFs during the metastasis of lung adenocarcinoma to the brain, it has several limitations." (PMID 33291558, 2020). "EZH2 and the EMT markers E-cadherin and Vimentin were examined by IHC in lung adenocarcinoma specimens that were resected from 2003–2012." (PMID 31042721, 2019). "In conclusion, using IHC, we demonstrated a significant correlation between EZH2 and EMT and their unfavorable correlations with lung adenocarcinoma prognosis." (PMID 31042721, 2019). "In general, downregulation of ZEB1, RECK, TGFBR2 and BMPR2, as well as upregulation of CDK4, CCNE2, EZH2 and DNMT1 has been shown in lung adenocarcinoma and/or squamous cell carcinoma." (PMID 27588394, 2016). "The relative mRNA levels of CBX2 and EZH2 were therefore assessed in SCLC and compared to two epithelial lung cancer subtypes, lung adenocarcinoma (AC) and squamous cell carcinoma (SqCC)." (PMID 25859291, 2015). "Studies have demonstrated that TFAP2A increases EZH2 expression by perturbing the activity of the NuRD complex to enhance hyperacetylation of the EZH2 promoter region and transcriptionally activate inositol 1,4,5-trisphosphate 3-kinase (ITPKA) and keratin 16 in lung adenocarcinoma (LUAD)." (PMID 37291585, 2023).
lung adenocarcinoma (continued). "We found that the expression of EZH2 is positively correlated with KRAS (r = 0.3167 and p < 0.001) and BRAF (r = 0.2397and p < 0.0001) gene expression in lung squamous cell carcinoma and lung adenocarcinoma." (PMID 33299862, 2020). "Further analysis found that the high expression of EZH2 was statistically significant in lung adenocarcinoma (HR = 1.27and 95% CI 1.01−1.6; p = 0.045), but not in lung squamous cell carcinoma (HR = 1.03 and 95% CI 0.81−1.3; p = 0.820)." (PMID 33299862, 2020). "The RNA-sequencing data of patients with NSCLC [502 patients with lung squamous cell carcinoma, including 49 paracancerous lung tissues and 513 patients with lung adenocarcinoma (LUAD), including 59 paracancerous lung tissues] from the Cancer Genome Atlas (TCGA), were analyzed for EZH2 expression." (PMID 33276757, 2020). "Epigenetic inducers such as H3K4 methyltransferase (MLL4, p = 0.018) and H3K36me3 demethylase (UTX, p = 0.003) were statistically increased, and epigenetic repressors such as EZH2 (H3K27 methyltransferase, p = 0.046) were significantly decreased in BM compared with those in lung adenocarcinoma." (PMID 33291558, 2020). "Importantly, our study showed a significant correlation between EZH2 expression and EMT, and furthermore, demonstrated combined effects of EZH2 and EMT on survival in clinical lung adenocarcinoma specimens." (PMID 31042721, 2019). "Although recent studies support the correlation between EZH2 expression and EMT, no reports have investigated their association using immunohistochemistry or explored their prognostic impact on lung adenocarcinoma." (PMID 31042721, 2019). "Thus, this study investigated correlations between EZH2 expression and the EMT status of resected lung adenocarcinoma specimens by immunohistochemical (IHC) staining, and their impacts on prognosis." (PMID 31042721, 2019). "MEK/ERK inhibition in lung adenocarcinoma lines with KRASG12C decreases EZH2 expression but is without affect in cell lines with KRASG12V." (PMID 29851957, 2018). "An attempt was made to replicate the results in a second validation series of stage I lung adenocarcinoma, but neither RRMI nor EZH2 were associated with survival in this second set." (PMID 30458017, 2018). "Expression of EZH2, which is frequently overexpressed in many cancers, was also significantly higher in subgroup F, indicating the importance of the E2F1-EZH2 network in the progression of lung adenocarcinoma." (PMID 22970185, 2012). "To further demonstrate the link between the three transcriptional regulators: MYC, EZH2 and YAP/TAZ and the tumor suppressor PTEN, we downloaded a list of transcripts and proteins positively or negatively correlated to PTEN in LUAD patients from the lung adenocarcinoma TCGA, Firehose Legacy study." (PMID 39455556, 2024). "In addition, human lung adenocarcinomas and lung squamous cell carcinomas in the NCI Clinical Proteomic Tumor Analysis Consortium (CPTAC) database displayed a significant inverse correlation (p < 0.0001) between the overall levels of EZH2 and DLC1 protein." (PMID 34862367, 2021). "Finally, we investigated whether EZH2 expression and EMT mutually affected the prognosis of lung adenocarcinomas." (PMID 31042721, 2019). "PVT1 recruited EZH2 to the large tumor suppressor kinase 2 (LATS2) promoter and repressed LATS2 transcription, and PVT1/EZH2/LATS2 interactions might serve as new target for lung adenocarcinoma diagnosis and therapy." (PMID 29046366, 2017). "However, the role of EZH2 has not been fully established in lung adenocarcinoma." (PMID 34943943, 2021). "However, the role of EZH2 has not been comprehensively established in lung adenocarcinoma." (PMID 33291558, 2020). "In accordance, both in lung adenocarcinoma (LUAD) and in lung squamous cell carcinoma (LUSC) patients, the EZH2 mRNA has a negative correlation with CTGF, ANKRD1 and CYR61 transcripts." (PMID 39455556, 2024).